FAM9C (family with sequence similarity 9 member C)
Synonyms: TEX39C
Tractability: No criterion of Open Targets' tractability assessment is met for any kind of drug.
Gene: Protein-coding gene on chromosome X (13,035,617 to 13,044,682, reverse strand). Ensembl gene ENSG00000187268.
Subcellular location: Nucleus
Gene Ontology:
Molecular function: protein binding
Biological process: meiotic cell cycle; spermatid development
Cellular component: synaptonemal complex; nucleus
Homologues: Orthologues: chimpanzee FAM9C (98% identical), macaque FAM9C (89% identical), tropical clawed frog sycp3 (27% identical), zebrafish sycp3 (24% identical), mouse Xlr3b (17% identical), mouse Xlr3a (16% identical), mouse Xlr3c (16% identical), mouse Xlr5b (16% identical), mouse Xlr5c (16% identical), rat LOC100911047 (16% identical), mouse Xlr5a (15% identical), rat Xlr4a (14% identical), and 8 more. Paralogues in human: FAM9A (60% identical), FAM9B (57% identical), SYCP3 (28% identical).
Diseases named in the same sentence as FAM9C in open-access papers:
FAM9C is named in the same sentence as 6 diseases in open-access papers, as found by Europe PMC text mining. Sharing a sentence is not in itself a finding about the gene and the disease. The quoted sentences say what the papers report.
ovarian insufficiency (1 paper, 2025). "Together, these data suggest FAM9C, ATP11C, and PAGE2B as potential candidate contributors to the ovarian insufficiency phenotype in TS and warrant further exploration." (PMID 40443572, 2025).
cancer (2 papers, 2017 to 2024). A tumor composed of atypical neoplastic, often pleomorphic cells that invade other tissues. "In addition, a literature search showed that FAM9C was identified to have several roles in cancer development such as promoting the tumor growth in the liver, while ARL15 was found to regulate adiponectin levels, which were dysregulated in cancer." (PMID 28981542, 2017).
FAM9C also shares sentences with these, for which no sentence is quoted: tumor (2 papers); breast carcinoma (1); Infertility (1); prostate carcinoma (1).